BRAF (B-Raf proto-oncogene, serine/threonine kinase)
Diseases named in the same sentence as BRAF in open-access papers (continued):
Sharing a sentence is not in itself a finding about the gene and the disease.
colorectal cancer (continued). "A high concordance rate between primary cancer and metastatic disease concerning driver mutations such as RAS or BRAF but also MSI has been reported from colorectal cancer." (PMID 36128324, 2022). "Mutations in PIK3CA are not mutually exclusive with BRAF mutations and occur in both BRAF mutated and wild type colorectal cancers." (PMID 36079062, 2022). "The gene mutation status of RAS and BRAF, two important molecular markers in colorectal cancer, showed a high degree of consistency between patients’ tumors and PDXs." (PMID 36465411, 2022). "Unrelated molecular alterations associated with sensitization of colorectal cancer cell lines to BRAF inhibitors included mutations in SACS, encoding for chaperone protein sacsin and deletions at the locus of parkin." (PMID 36295658, 2022). "It is well established that this limited activity of BRAF inhibitor monotherapy in BRAF-mutant colorectal cancer is associated with activation of epidermal growth factor receptor (EGFR)-mediated signaling." (PMID 36045401, 2022). "We observed significant differences between the association of diabetes and colorectal cancer by BRAF‐mutation status for colon (Pdifference = .04) and proximal colon cancers (Pdifference = .02)." (PMID 35383926, 2022). "Identifying particular patient subsets also provides opportunity to understand the natural history of that biomarker subset, such as the impact of a BRAF V600E mutation in early stage or advanced colorectal cancer." (PMID 36077668, 2022). "In fact, Fusobacterium nucleatum signatures in proximal colorectal cancer tissue are correlated with shorter patient survival and molecular alterations such as hypermutation with microsatellite instability and BRAF mutations." (PMID 35752764, 2022). "Second, we were not able to evaluate CMS categories or genomic alterations such as microsatellite instability and KRAS and BRAF mutations that are important for precise characterization of colorectal cancer." (PMID 36052235, 2022). "BRAF mutations are present in approximately 10% of colorectal cancers, again raising the possibility of using BRAF inhibitor and MEK inhibitor." (PMID 35492830, 2022). "In summary, our study confirms the established association between diabetes and colorectal cancer risk and suggests that it especially increases the risk of BRAF‐mutated tumors." (PMID 35383926, 2022). "Colorectal cancers with mutations in BRAF tend to be of high grade and occur more often in the right colon." (PMID 36295658, 2022). "In total, 22 of 534 profiled colorectal cancer patients in the TCGA cohort (4.1%) had mutations in both BRAF and PIK3CA oncogenes." (PMID 36079062, 2022). "Preclinical models of BRAFV600E mutated colorectal cancer have shown that BRAF inhibition causes rapid feedback activation through the epidermal growth factor receptor (EGFR)." (PMID 35492830, 2022). "These analyses allowed to identify several interesting molecular subgroups (e.g., colorectal cancer with BRAF and RNF43 mutations), however, the limited clinical annotations in the dataset did not allow to further clinically define these subgroups." (PMID 36275468, 2022). "BRAF mutated colorectal cancers are less prevalent, representing 5% to 15% of all colorectal cancers." (PMID 36295658, 2022). "The compounds potently inhibited BRAFV600E, HDAC1, and HDAC6 enzymes and suppressed the proliferation of colorectal cancer cells harboring both wide-type BRAF and V600E mutated BRAF." (PMID 35936102, 2022). "In the era of immunotherapy, the impact of immune cell infiltrations in BRAF-mutated colorectal cancers is questioned." (PMID 35461290, 2022). "Colorectal cancers (CRCs) harboring BRAF V600E mutations are aggressive cancers with rapid metastatic spread that more frequently involves peritoneal and nodal invasion than liver metastases." (PMID 35461290, 2022). "The colorectal cancer cohort of CCLE consisting of 84 cell lines contains 23 cell lines (27.4%) with BRAF mutations." (PMID 36295658, 2022).
colorectal cancer (continued). "A detailed understanding of the molecular processes associated with these distinct subsets of colorectal cancers and additional molecular aberrations that support BRAF mutations in the neoplastic process is needed for improving therapeutic results." (PMID 36079062, 2022). "In this literature review, we investigated the relationship between BRAF mutation and prognosis in patients with colorectal cancer liver metastases." (PMID 36077604, 2022). "The Japanese Society for Colorectal Cancer (JSCRC) (2019) guideline recommends the combination FOLFOXIRI-bevacizumab in the first-line treatment of BRAF mutated mCRC, according to the results of the TRIBE study." (PMID 36819812, 2022). "It is worth noting that individuals reporting diabetes had a higher risk of all subtypes of colorectal cancer and the difference related to BRAF‐mutated tumors only affected the magnitude of the risk, but the direction remained the same." (PMID 35383926, 2022). "HT-29 cells overexpress EGFR and are representative of wildtype-KRAS and BRAF-mutated tumours, which have been reported in approximately 5-15% of patients with colorectal cancers." (PMID 36591314, 2022). "Regarding the prevalence of mutations in other commonly mutated oncogenes and tumor suppressors, there are significant differences between colorectal cancers depending on the presence of BRAF and PIK3CA mutations." (PMID 36079062, 2022). "We show that AI models trained using SL can predict BRAF mutational status and microsatellite instability directly from hematoxylin and eosin (H&E)-stained pathology slides of colorectal cancer." (PMID 35469069, 2022). "BRAF mutations are targeted currently in colorectal cancer in the clinic at the second line metastatic setting with a regimen that combines BRAF inhibitors and anti-EGFR monoclonal antibodies." (PMID 36295658, 2022). "It has been shown that BRAF mutations in codons 594 and 596 significantly differ from V600E in terms of molecular, pathological, and clinical features in colorectal cancer." (PMID 35163468, 2022). "Colorectal cancer carrying BRAF V600E mutation intrigued many researchers due to its poor prognosis." (PMID 36130926, 2022). "The BRAF mutations in skin and colorectal cancer likewise sensitize to different BRAF inhibitors in both the GDSC and PRISM drug data, and also to BRAF gene disruption." (PMID 35614096, 2022). "Mismatch-repair-associated gene mutations display higher frequencies in BRAF mutated colorectal cancers." (PMID 36079062, 2022). "Our study shows that higher levels of NNMT expression tend to be found in colorectal cancers with BRAF mutations or CIMP-high and/or MSI genomic background." (PMID 35177765, 2022). "All patients (N = 1035) were diagnosed with colorectal cancer and the mutation status of BRAF was determined." (PMID 36130926, 2022). "BRAF V600E-mutant colorectal cancers (CRCs) are associated with shorter survival than BRAF wild-type tumors." (PMID 35461290, 2022). "In total, 20 of the 24 ATM mutations (83.3%) in BRAF mutated colorectal cancers are categorized as likely oncogenic." (PMID 36079062, 2022). "Another genomic feature that is present recurrently among the abnormalities conferring BRAF inhibitor sensitivity in colorectal cancer cell lines is mutations in SACS, a gene encoding for sacsin, a chaperone protein." (PMID 36295658, 2022). "In the second, the presence of gene fusions and oncogenic mutations in MLH1-deficient and BRAF V600E wild-type colorectal cancers were assessed." (PMID 36612287, 2022). "For instance, while BRAF V600 mutations are targetable by BRAF inhibitors in multiple hematologic and solid cancers, ORRs are low in colorectal cancer." (PMID 36045401, 2022). "The aim of the present study was to investigate self‐reported diabetes status in relation to molecular tumor traits in colorectal cancer (BRAF and KRAS mutations, MSI status and CpG island methylator phenotype [CIMP])." (PMID 35383926, 2022).
colorectal cancer (continued). "BRAF mutations are observed in 5% to 15% of colorectal cancers and are associated with aggressive disease." (PMID 36295658, 2022). "In this manner, the IdyllaTM mutation tests were validated for the detection of clinically significant KRAS, NRAS, and BRAF mutations in FFPE samples from colorectal cancer patients." (PMID 35474548, 2022). "Mutations in BRAF occur in about 10% of colorectal cancers and have been examined for therapeutic targeting with the same small molecule inhibitors used in melanoma." (PMID 36079062, 2022). "This suggests that ATM mutations in BRAF mutated colorectal cancers are associated with a better prognosis sub-group such as MSI high." (PMID 36079062, 2022). "In colorectal cancer samples, the author observed a trend towards mutual exclusivity for BRAF and KRAS mutations." (PMID 36275468, 2022). "On the other hand, approximately 10% of colorectal cancer patients harbor a variant of the BRAF gene." (PMID 35893795, 2022). "It is also mutated in 33.9% of colorectal cancers with BRAF mutations and in 19% of cancers with PIK3CA mutations." (PMID 36295658, 2022). "We identified 53 patients with BRAF mutation bearing colorectal cancer (CRC), of which 51 (96%) had NGS identified BRAF mutations that would be detected on the Idylla system if performed." (PMID 35627184, 2022). "Our primary finding was a statistically significant difference in the strength of the association between reported diabetes status and colorectal cancer by BRAF status, with a stronger association for BRAF‐mutated than nonmutated tumors." (PMID 35383926, 2022). "As RS primary tumors are more frequently associated with BRAF-mutations than the LS colorectal cancers, that can tip the balance of OS and SAR in favor of the LS group." (PMID 36013567, 2022). "A high prevalence of ATM mutations is observed in BRAF mutated colorectal cancers in both TCGA and DFCI cohorts." (PMID 36079062, 2022). "The mutation status of RAS and BRAF genes is considered to be of great significance in guiding the treatment and predicting the prognosis of colorectal cancer patients." (PMID 36465411, 2022). "Loss of PRKN is a feature of some BRAF mutant cell lines and it is also, rarely, encountered in BRAF mutant colorectal cancers." (PMID 36295658, 2022). "BRAF mutations are linked to more advanced and aggressive colorectal cancer, lung cancer, and thyroid carcinoma." (PMID 35936102, 2022). "In April 2020, the FDA approved encorafenib in combination with cetuximab for patients with pretreated advanced colorectal cancer harboring a BRAF V600E mutation." (PMID 36045401, 2022). "Consistent with the high prevalence of MSI and POLE subtype, BRAF/PIK3CA double mutant colorectal cancers in TCGA had a high Tumor Mutation Burden (TMB) above 200 in 86.4% of cases." (PMID 36079062, 2022). "Another limitation of the current study is that it relies only upon CRCs with BRAF mutation, which represent a minor fraction of all colorectal carcinomas." (PMID 36010943, 2022). "Sex, histological type, histological grade, microsatellite instability, and tumor mutation burden of the patients harboring KRAS-mutant, BRAF-mutant, and double-mutant colorectal carcinoma varied significantly." (PMID 35280113, 2022). "In colorectal cancer patients with BRAF mutation, double therapy (encorafenib 200 mg/day + cetuximab) and triple therapy (encorafenib 200 mg/day + alpelisib 300 mg/day + cetuximab) showed good clinical efficacy and safety." (PMID 34976824, 2021). "Mutation of the BRAF proto-oncogene is found in approximately 10% of colorectal cancers (CRC), with much of the mutation conferred by a V600E mutation." (PMID 34975492, 2021).
colorectal cancer (continued). "As KRAS and BRAF mutations are found in approximately 40% and 10% of human colorectal cancers (CRCs), respectively, the therapeutic use of vitamin C in treating patients with colorectal cancer presenting such type of mutations seems to be rational." (PMID 33652579, 2021). "For example, BRAF mutation has been proven to be a vital factor affecting chemotherapeutic resistance and survival rate of colorectal cancer and non-small-cell lung cancer." (PMID 34925539, 2021). "Although the BEACON trial showed an improvement in overall survival associated with doublet therapy for metastatic BRAF variant colorectal cancer, the model created in this economic evaluation suggested that doublet therapy was unlikely to be cost-effective." (PMID 33433598, 2021). "The BRAF-mediated MEK/ERK-mediated MCL-1 upregulation is the production mechanism of colorectal cancer cell resistance that causes BRAF mutations." (PMID 34976824, 2021). "Second, limited data were available on the survival of patients with BRAF variant colorectal cancer who received regorafenib." (PMID 33433598, 2021). "Regarding undifferentiated colorectal cancer with Rhabdoid features, BRAF V600VE mutation was observed in 6 of 7 reported cases." (PMID 33903966, 2021). "Patients mirrored the cohorts in the BEACON trial: they had metastatic BRAF variant colorectal cancer and were followed up as they progressed through multiple lines of therapy, best supportive care, and death." (PMID 33433598, 2021). "Without broad changes to drug pricing, the costs associated with doublet therapy are unlikely to represent reasonable value for the setting of relapsed metastatic BRAF variant colorectal cancer." (PMID 33433598, 2021). "Colorectal cancers with BRAF mutations have higher glucose uptake on [18F]fluorodeoxyglucose positron emission tomography (FDG-PET) than those without BRAF mutations." (PMID 33420213, 2021). "BRAF mutations occur in a minority of colorectal cancers cases (5-15%) compared to KRAS mutations in codon 12 and 13 (40%) and extended KRAS and NRAS mutations (52%)." (PMID 34535182, 2021). "We summarize recent knowledge regarding the effects of KRAS and BRAF mutations in the setting of colorectal cancer and discuss the new therapies under development." (PMID 34063682, 2021). "The BEACON trial showed that combination therapy with encorafenib (BRAF inhibitor) and cetuximab (EGFR inhibitor) was associated with prolonged overall survival compared with standard chemotherapy in patients with metastatic BRAF variant colorectal cancer." (PMID 33433598, 2021). "This economic evaluation uses Markov modeling to identify and compare the cost and utility of doublet and standard treatments for patients with BRAF V600E variant colorectal cancer." (PMID 33433598, 2021). "The analysis focused not only on tumor location, mucin phenotype, and PD-L1 status but also on factors such as KRAS and BRAF mutations, which are important in colorectal cancer." (PMID 34797780, 2021). "In this regard, the activation of BRAF, a proto-oncogene strongly linked to CD-associated colorectal cancer, has been shown to override RAF1 signalling and activate MEK1/272,73." (PMID 34075172, 2021). "It has been shown that an increase in glucose uptake through enhanced GLUT1 expression is dependent on KRAS and BRAF mutation in colorectal cancer cell lines and sustained their survival." (PMID 33777798, 2021).
colorectal cancer (continued). "Treatment recommendations for special populations: v-raf murine sarcoma viral oncogene homolog B (BRAF) mutation was critical in patients with advanced colorectal cancer." (PMID 34567559, 2021). "MLH1-deficient colorectal cancers were prescreened for BRAF V600E before referral for genetic counseling." (PMID 34397043, 2021). "Further, missing molecular characteristics such as BRAF mutation have been established as major determinants of therapy response and survival in colorectal cancer." (PMID 34956863, 2021). "High levels of vitamin C have been found to selectively kill colorectal cancer cells harboring KRAS or BRAF mutations." (PMID 33777798, 2021). "In mouse models of colorectal cancer with BRAF V600E mutations, cobimetinib combined with MCL-1 antagonists showed good drug-resistant antagonism." (PMID 34976824, 2021). "Colorectal cancer cells with KRAS or BRAF mutations show enhanced glucose metabolism such as glucose uptake and glycolysis, and require expression of glucose transporter-1 (GLUT-1), a membrane glucose transporter." (PMID 33420213, 2021). "In a KRAS/BRAF mutated colorectal cancer cell model, a reversible oxidation of GAPDH was observed after vitamin C treatment." (PMID 33804775, 2021). "In colorectal cancer, a positive correlation was found between oncogenic BRAF mutations and hypermethylation of multiple promoter CpG islands, known as CpG island methylator phenotype." (PMID 33397444, 2021). "This review aims to highlight the recent findings that have improved our understanding of KRAS and BRAF mutations in colorectal cancer and to describe new targeted therapies, used alone or in combination." (PMID 34063682, 2021). "CT image texture parameters of colorectal cancer have certain correlation with KRAS/NRAS/BRAF gene mutations in colorectal cancer, and the texture parameters extracted from MRI images can help predict TCGA/TCIA molecular subtypes in breast cancer." (PMID 34307164, 2021). "Unfortunately, the effect of PLX4032 in the treatment of metastatic BRAF mutated colorectal cancer (CRC) is less potent due to high incidence of fast-developing chemoresistance." (PMID 34639107, 2021). "Is the use of doublet therapy (encorafenib and cetuximab) compared with standard chemotherapy (with cetuximab and irinotecan-based regimens) a cost-effective treatment strategy in patients with metastatic BRAF variant colorectal cancer?" (PMID 33433598, 2021). "Concurrently, NCCN guidelines recommend FOLFOXIRI combined with bevacizumab as the first-line treatment regimen of colorectal cancer patients with the BRAF V600E mutation and ECOG PS score 0–1." (PMID 34567559, 2021). "BRAF V600E-mutated colorectal cancers are a relatively rare finding but often present with characteristic clinical features, histopathology and imaging findings." (PMID 34535182, 2021). "Mutation in KRAS, NRAS, and BRAF has been demonstrated to be involved in initiation and progression of colorectal carcinoma." (PMID 33816307, 2021). "We present the mediator probe (MP) PCR for the quantification of the seven most frequent point mutations and corresponding wild types (KRAS and BRAF) in colorectal carcinoma." (PMID 34830896, 2021). "Cocco and co-workers reported a 5% fusion detection in MSI/MMR-deficient colorectal carcinoma and 15% MSI/MMR-deficient colorectal carcinoma with wild-type RAS/BRAF." (PMID 34282766, 2021). "Previous studies reported that approximately 10–11% of advanced colorectal cancers showed intratumoral heterogeneity of KRAS or BRAF mutations where mutations were identified in only one of the multiple formalin‐fixed, paraffin‐embedded tumor blocks." (PMID 32449983, 2020). "For example, the Bayesian model highlighted the association between BRAF mutation in colorectal cancer and BRAF inhibitor response." (PMID 33274713, 2020).